TRIM33 (tripartite motif containing 33)
Diseases named in the same sentence as TRIM33 in open-access papers (continued):
Sharing a sentence is not in itself a finding about the gene and the disease.
clear cell renal cell carcinoma (6 papers, 2019 to 2025). "In renal clear cell carcinoma, TRIM33 regulates tumor progression by inhibiting the TGF-β/Smad pathway and the Wnt signaling pathway." (PMID 39062881, 2024). "Research into clear cell renal cell carcinoma (ccRCC) showed that TRIM33 is upregulated by treatment with an inhibitor named miR-629, which notably suppresses TGFβ-induced Smad activation as well as facilitating metastasis of ccRCC." (PMID 37573347, 2023). "In renal clear cell carcinoma, studies have shown that TRIM33 is a direct target of miR-629 and affects tumor progression by inhibiting the TGF-β/Smad pathway." (PMID 32908919, 2020). "In summary, these findings indicate that TRIM33 overexpression can exhibit antitumor activity by inhibiting the Wnt/β-catenin pathway in renal clear cell carcinoma." (PMID 32908919, 2020). "In particular, we also plotted the potential mechanism of TRIM33 in renal clear cell carcinoma cells." (PMID 32908919, 2020). "From this experiment, we learned that TRIM33 plays a role in inhibiting the development of renal clear cell carcinoma both in vivo and in vitro." (PMID 32908919, 2020). "For instance, overexpression of TRIM33 could suppress the proliferation, migration and invasion of clear cell renal cell carcinoma cells." (PMID 35333698, 2022). "Similarly, our study shows that TRIM33 can inhibit the progression of renal clear cell carcinoma by inhibiting the activity of the Wnt/β-catenin pathway." (PMID 32908919, 2020). "Unlike previous studies of renal clear cell carcinoma, for the first time, it was found that upregulation of TRIM33 inhibited the expression of β-catenin, cyclin D1, and c-myc molecules in the Wnt signaling pathway." (PMID 32908919, 2020).
HIV-1 infection (6 papers, 2019 to 2025). The type species of lentivirus and the etiologic agent of acquired immunodeficiency syndrome (AIDS). "In multiple BRU HIV-1 infection experiments, TRIM33 knockdown also increased IN levels and promoted infection, whereas TRIM33 overexpression in KD cells impaired infection." (PMID 39599797, 2024). "TRIM33 inhibits HIV-1 infection by ubiquitinating and inducing the proteasomal-mediated degradation of the viral integrase, thus preventing viral cDNA integration into the cellular genome." (PMID 37410772, 2023). "Currently there are several cellular proteins known as restriction factors that have been extensively studied with regards to HIV-1 infection: TRIM5α; TRIM33; SAMHD1; MARCH8, APOBEC3 proteins and tetherin." (PMID 34066177, 2021). "Our work indicates that TRIM33 suppresses HIV-1 infection by promoting ubiquitin/proteasome-mediated degradation of IN, thus preventing proviral formation." (PMID 30804369, 2019). "Additionally, TRIM33 restrains HIV-1 infection by targeting viral integrase, while TAF3, a transcription cofactor, contributes to promotor recognition and selectivity." (PMID 39996757, 2025). "Thus, TRIM33 acts as a cellular factor restricting HIV-1 infection by preventing provirus formation." (PMID 30804369, 2019). "Thus, TRIM33 acts as an inhibitory factor hampering HIV-1 infection by decreasing IN function and thus preventing viral cDNA integration into the host cell genome." (PMID 30804369, 2019). "We wanted to understand the role of TRIM33 in HIV-1 infection." (PMID 30804369, 2019). "High throughput screening of a human siRNA library targeting all known components of the ubiquitin conjugation system has revealed that the TRIM33 RING finger E3 ligase is responsible for HIV-1 IN degradation and thus acts an inhibitory factor for HIV-1 infection by preventing viral DNA integration." (PMID 30804369, 2019).
liver cancer (6 papers, 2019 to 2024). An epithelial or non-epithelial malignant neoplasm that arises from the liver. "At the same time, the decreased expression of TRIM33 is an independent and significant risk factor for recurrence and survival after radical resection of liver cancer." (PMID 39389957, 2024). "Recent studies have found that TRIM33 gene is lowly expressed in liver cancer and chronic myelogenous leukemia, and knocking out TRIM33 gene in mice can lead to the occurrence of liver cancer in mice." (PMID 36301038, 2022).
colon cancer (5 papers, 2020 to 2025). "For example, the drug mesalazine, used to treat inflammatory bowel disease but with an apoptosis-inducing and chemopreventative effect in colon cancer; DTI-Voodoo predicts mesalazine to interact with five proteins with PHD-type zinc finger domain: BRPF1, TRIM33, BAZ1A, RSF1 and DPF2." (PMID 34320178, 2021).
colorectal cancer (5 papers, 2015 to 2024). A primary or metastatic malignant neoplasm that affects the colon or rectum. "Increased expression of TRIM33 in colorectal cancer is associated with the loss of Smad4 and indicates a poor prognosis in patients with colorectal cancer." (PMID 39389957, 2024). "In this study, loss of TRIM33 correlated with resistance to BET inhibitors in colorectal cancer." (PMID 32731534, 2020). "For example, TRIM33 is highly expressed in colorectal cancer, and its expression level is related to tumor stage." (PMID 39389957, 2024). "Contrastingly, in B lymphoblastic leukaemia (B-ALL) TRIM33 plays an oncogenic role by preventing apoptosis and TRIM33 expression was higher in advanced stages of colorectal cancer compared to earlier stages." (PMID 32731534, 2020). "TRIM33 has also been proposed as a predictor of response to bromodomain and extra-terminal (BET) inhibitors in colorectal cancer." (PMID 32731534, 2020). "Contrastingly, in colorectal cancer cells knockdown of TRIM33 did not affect γH2AX levels, highlighting the cell-type specificity of TIF1 protein function." (PMID 32731534, 2020).
glioma (5 papers, 2016 to 2023). A benign or malignant brain and spinal cord tumor that arises from glial cells (astrocytes, oligodendrocytes, ependymal cells). "TRIM33 (class VI) is implicated in neural stem cell and glioma regulation via the TGFβ/SMAD4 and β-Catenin signaling pathways, respectively." (PMID 38115822, 2023). "IGFBP2 and IGFBP2-induced TRIM33 were associated with stemness induction of glioma cells." (PMID 36139694, 2022). "The TRIM33-mediated nuclear β-catenin degradation leads to the suppression of glioma cell proliferation." (PMID 36139694, 2022). "Knowledges about beta-catenin regulation in glioma are recently increasing with R132H IDH1 mutation, FoxM1, TRIM33, HOXA13 as examples of positive or negative regulators." (PMID 27613837, 2016).
renal cell carcinoma (5 papers, 2017 to 2025). "TRIM33 expression is decreased in renal cell carcinoma, and overexpression of TRIM33 in renal cell carcinoma can affect the proliferation, migration, and invasion of cancer cells by inhibiting the Wnt/β‐catenin pathway." (PMID 36301038, 2022). "In order to understand the expression of TRIM33 in pan-cancer and renal cell carcinoma and the relationship between its expression and clinical characteristics, we used the online tool on UALCAN's website." (PMID 32908919, 2020). "In addition, we found that there was a correlation between the expression levels of TRIM33 in renal cell carcinoma and two clinical features, tumor size (P = 0.031) and Furman's grade (P = 0.036)." (PMID 32908919, 2020).
viral infection (5 papers, 2017 to 2025). "The interaction among TRIM24, TRIM28, and TRIM33 forms a functionally significant complex that critically regulates viral infections and other cellular processes." (PMID 40421416, 2025). "We found that both TRIM33 and IN co-immunoprecipitated with the respective partners during viral infection." (PMID 30804369, 2019). "Together with the role of TRIM33 during viral infection, these results pinpoint TRIM33 as a new clinical target for infectious diseases." (PMID 27974684, 2017). "Although TRIM24 and TRIM33 SUMOylation have been shown to influence chromatin interaction and TGFβ signaling, respectively, their roles in viral infections remain underexplored." (PMID 40421416, 2025). "Indeed, TRIM33 has been shown to regulate NLRP3 inflammasome activation in response to bacterial or viral infection through a direct interaction with DHX33 in the cytoplasm and to regulate Ifnb1 transcription at the late stages of BMDM activation." (PMID 27974684, 2017). "In this review, we focus on Class VI TRIM proteins, including TRIM24, TRIM28, and TRIM33, highlighting the distinct functional attributes of their RING, B-BOX1, B-BOX2, COILED COIL, PHD, and BRD domains in viral infection." (PMID 40421416, 2025). "However, during viral infections, phosphorylation is predominantly observed in TRIM28, with fewer reports in TRIM33." (PMID 40421416, 2025).
autoimmune disease (4 papers, 2015 to 2025). A disorder resulting from loss of function or tissue destruction of an organ or multiple organs, arising from humoral or cellular immune responses of the individual to their own tissue constituents. "Interestingly, Bim is upregulated as a means to eliminate auto-reactive B cells and to prevent autoimmune disease, suggesting a rationale for precise modulation of enhancer activity at the Bim locus by TRIM33 to regulate adaptive immunity." (PMID 25919951, 2015).
brain tumor (4 papers, 2021 to 2023). "Another instance is tripartite motif-containing protein 33 (TRIM33), which is a transcriptional corepressor suppressor of brain tumor development that can distinguish PA from the more aggressive diffuse gliomas." (PMID 36772521, 2023). "Among the proteins found significantly associated to PA, the tripartite motif-containing protein 33 (TRIM33), is a transcriptional corepressor suppressor of brain tumor development." (PMID 33469081, 2021). "For the third member of the group C-VI, TRIM33 (TIF1γ, also known as RFG7, PTC7, or Ectodermin), a tumor suppressor potential has been recently suggested in brain tumors." (PMID 36139694, 2022).
idiopathic inflammatory myopathies (4 papers, 2020 to 2024). "TRIM33 is bound up with various diseases, such as human cancers, idiopathic inflammatory myopathies and colonic inflammation." (PMID 34101965, 2021). "Anti-TIF-1γ autoantibodies (also anti-TRIM33 or anti-p155/140 autoantibodies) were first described in 2006 when a large cohort of patients with idiopathic inflammatory myopathies was examined by immunoprecipitation (IP)." (PMID 33613568, 2020).
leukaemia (4 papers, 2005 to 2024). "One of the PU.1/TRIM33 co-occupied enhancers is upstream of the pro-apoptotic gene Bim, and deleting this enhancer renders TRIM33 dispensable for leukemia cell survival." (PMID 25919951, 2015). "Developing drugs that prevent TRIM33 from working could therefore provide new options for treating leukemia." (PMID 25919951, 2015). "This differential Cre expression results in leukemia in the cFES-Cre mediated Trim33 knock-out whereas MxCre/Trim33−/− mice never developed myelomonocytic leukemia." (PMID 27974684, 2017).
multiple myeloma (4 papers, 2018 to 2024). "Similarly, we have shown that multiple myeloma cell lines with low TRIM33 expression have higher endogenous DNA damage as assessed by γH2AX levels." (PMID 32731534, 2020).
B-cell neoplasm (3 papers, 2015 to 2021). A group of heterogeneous lymphoid tumors generally expressing one or more B-cell antigens or representing malignant transformations of B-lymphocytes. "We next evaluated the mechanism underlying the essential TRIM33 function in B cell neoplasms." (PMID 25919951, 2015). "TRIM33 is identified here as a lineage dependency in B cell neoplasms and is shown to perform this essential function by associating with a single cis element." (PMID 25919951, 2015). "Nonetheless, our findings justify consideration of TRIM33-inhibition as a therapeutic approach in B cell neoplasms, which would be expected to unleash an apoptosis-promoting enhancer element." (PMID 25919951, 2015).
kidney cancer (3 papers, 2020 to 2025). Primary or metastatic malignant neoplasm involving the kidney. "Gain-of-function study in 786-O and ACHN kidney cancer cells lines also showed that TRIM33 overexpression inhibited cell proliferation, migration, and invasion of these cancer cells." (PMID 40723250, 2025). "It was observed that the expression of TRIM33 in the three kidney cancer cell lines was significantly lower than that in normal renal tubular epithelial cells." (PMID 32908919, 2020). "We found that TRIM33 overexpression inhibited cell migration and invasion in two kidney cancer cell lines." (PMID 32908919, 2020). "TRIM33 showed significantly lower expression in kidney cancer tissues than in normal tissues, and its expression levels were significantly associated with multiple clinical features." (PMID 32908919, 2020). "We found that the migration and invasion abilities of the two kidney cancer cell lines overexpressing TRIM33 were significantly inhibited." (PMID 32908919, 2020). "Through western blot experiments, we found that TRIM33 overexpression in two kidney cancer cell lines resulted in the upregulation of the expression of E-cadherin and downregulation of the expression of N-cadherin and vimentin." (PMID 32908919, 2020). "Subsequently, we used 80 collected kidney cancer tissues and multiple kidney cancer cell lines to evaluate the expression levels of TRIM33." (PMID 32908919, 2020). "The results showed that TRIM33 was significantly downregulated in kidney cancer tissues and cell lines, and its expression was correlated with tumor size and Furman's grade." (PMID 32908919, 2020). "Our study indicates that TRIM33 plays a role as a tumor suppressor gene in ccRCC and may become a potential target and prognostic marker for kidney cancer treatment in the future." (PMID 32908919, 2020). "Based on the effects of TRIM33 on the proliferation of kidney cancer cells, we conducted a series of experiments to investigate whether TRIM33 overexpression affects the migration and invasion of two kidney cancer cell lines." (PMID 32908919, 2020). "Among them are TRIM2 (up-regulated in osteosarcoma, down-regulated in kidney cancer), TRIM29 (up-regulated in lung cancer and osteosarcoma, down-regulated in liver and prostate cancers), TRIM33 (up-regulated in breast cancer, down-regulated in liver and kidney cancers)." (PMID 33673719, 2021).
melanoma (3 papers, 2020 to 2026). A malignant, usually aggressive tumor composed of atypical, neoplastic melanocytes. "Another example of fusion visualization in the KC is a 38-year-old female with melanoma and a TRIM33::BRAF fusion between two amplified genomic regions (TCN of 8 in an inferred diploid genome)." (PMID 41554728, 2026). "To identify whether TRIM24HIGH, TRIM33HIGH, or TRIM66HIGH melanoma phenotype reflected the one observed in TRIM28HIGH expressing melanomas, we searched for genes that correlate with the expression of TRIM24, TRIM33, TRIM66, and TRIM28 in SKCM TCGA data." (PMID 33076560, 2020). "Interestingly, the expression of other close-related TRIM family members’ (namely, TRIM24, TRIM33, and TRIM66) does not correlate with the survival of melanoma patients, suggesting that TRIM28 is specifically involved in melanoma progression." (PMID 33076560, 2020).
osteoporosis (3 papers, 2021 to 2025). A condition of reduced bone mass, with decreased cortical thickness and a decrease in the number and size of the trabeculae of cancellous bone (but normal chemical composition), resulting in increased fracture incidence. "In general, our findings expounded that TRIM33 protected osteoblasts against oxidative stress‐induced apoptosis in osteoporosis and that the underlying mechanism was the restraint of FOXO3a ubiquitylation and degradation." (PMID 34101965, 2021). "This study aimed to probe into the effect of TRIM33 on oxidative stress‐induced apoptosis of osteoblasts in osteoporosis and to probe into the underlying mechanism." (PMID 34101965, 2021). "However, the effect of TRIM33 on oxidative stress‐induced apoptosis of osteoblasts in osteoporosis and the underlying mechanisms remain largely unknown." (PMID 34101965, 2021). "TRIM33 attenuated oxidative stress-induced osteoblast apoptosis in osteoporosis by blocking FOXO3a ubiquitination and degradation." (PMID 35333698, 2022). "The results expounded that TRIM33 protected osteoblasts from oxidative stress‐induced apoptosis in osteoporosis." (PMID 34101965, 2021). "Western blot analysis confirmed a low expression of TRIM33 in the osteoblasts of patients with osteoporosis." (PMID 34101965, 2021). "Here, we found that TRIM33 expression was lessened in the osteoblasts of patients with osteoporosis and was positively correlated with the bone mineral density of these patients." (PMID 34101965, 2021). "In summary, this study corroborated a protective role of TRIM33 against the oxidative stress‐induced apoptosis of osteoblasts in osteoporosis." (PMID 34101965, 2021). "Thus, this is the first study to elucidate the effect of TRIM33 on osteoporosis and oxidative stress‐induced apoptosis of osteoblasts." (PMID 34101965, 2021). "Then, we probed into the role of TRIM33 in osteoporosis in vivo." (PMID 34101965, 2021). "However, the effect of TRIM33 on osteoporosis and the oxidative stress‐induced apoptosis of osteoblasts has not been reported so far." (PMID 34101965, 2021). "Here, we corroborated that TRIM33 expression was lessened in the osteoblasts of patients with osteoporosis and OVX mice and was positively correlated with the BMD of patients with osteoporosis." (PMID 34101965, 2021). "We then analyzed the correlation between TRIM33 expression and the BMD of patients with osteoporosis." (PMID 34101965, 2021).
acute lymphoblastic leukemia (2 papers, 2015 to 2026). Leukemia with an acute onset, characterized by the presence of lymphoblasts in the bone marrow and the peripheral blood. "In contrast, TRIM33 knockdown led to negligible effects on the viability of MLL-AF9/NrasG12D AML and Notch-mutant T-cell acute lymphoblastic leukemia (T-ALL)." (PMID 25919951, 2015).
adenovirus infection (2 papers, 2013 to 2023). "In addition, TRIM33 limits adenovirus gene expression and its degradation is caused by a variety of adenoviruses, suggesting that it is a restriction factor for adenovirus infection." (PMID 37410772, 2023). "TRIM33, also called Trancriptional Intermediary Factor 1γ (TIF1γ), has been described to display an anti-viral activity limiting early and late gene expression in a human adenovirus infection model." (PMID 24015922, 2013). "Interestingly, a similar shift in mobility of TRIM33 is seen in response to adenovirus infection, which also results in TRIM33 SUMOylation and proteasomal degradation, although the nature of this shift was not determined." (PMID 37410772, 2023).
breast tumors (2 papers, 2021 to 2024). "One report cites TRIM33 levels as being decreased in breast tumors relative to normal breast tissue." (PMID 38473207, 2024). "TRIM33 expression was firstly described as decreased in breast tumors, compared to normal breast tissues." (PMID 34208621, 2021). "Numerous TRIMs were found to be overexpressed in breast tumors, compared to normal breast tissue: TRIM11, TRIM32, TRIM33, TRIM37, TRIM39, TRIM44, TRIM47 and TRIM63." (PMID 34208621, 2021).
colitis (2 papers, 2021 to 2025). Inflammation of the colon. "For example, Trim33-/- mice contain monocytes that do not differentiate into colonic MPs and display impaired resolution of colonic inflammation in DSS-induced colitis." (PMID 34650568, 2021).
lung adenocarcinoma (2 papers, 2019 to 2020). A carcinoma that arises from the lung and is characterized by the presence of malignant glandular epithelial cells. "This collection included the previously reported LC-2/ad cell line that harbors a CCDC6-RET fusion (xxxxx) as well as two novel patient-derived cell lines generated by us, i.e. ECLC5B harboring TRIM33-RET and PDX-derived lung adenocarcinoma cells harboring KIF5B-RET (LUAD-0002AS1)." (PMID 33318047, 2020).